TEP1 (telomerase associated protein 1)
Diseases named in the same sentence as TEP1 in open-access papers (continued):
Sharing a sentence is not in itself a finding about the gene and the disease.
infection (54 papers, 2009 to 2025). The state of being infected such as from the introduction of a foreign agent such as serum, vaccine, antigenic substance or organism. "Case 6 has a sibling with PANS who also developed infection-induced catatonia, who has the TEP1, BTNL9 and VNN1 variants." (PMID 40894167, 2025). "High recombination events in An. gambiae TEP1 gene was suggested to promote higher infection prevalence relative to homozygote TEP1r allele." (PMID 36899431, 2023). "TEP1*S3 allele closely related to TEP1*S1 is fixed in the G3 strain associated with susceptibility of infection to Plasmodium berghei." (PMID 35948910, 2022). "TEP1 expression followed the same pattern as LRIM1 while APL1C additionally showed differential upregulation in the midgut associated with infection at 24 hpbm." (PMID 34174879, 2021). "It was shown that the central mosquito complement component, thioester-containing protein 1 (TEP1), was strongly associated with protecting mosquitoes from infection by both rodent and human parasites." (PMID 32891162, 2020). "We conclude that African P. falciparum strains vary in their susceptibility to TEP1-mediated killing and that the outcome of infection depends on the combination of genetic backgrounds of both mosquitoes and parasites." (PMID 26861587, 2016). "Ngousso strain is a mix of TEP1*S alleles (0,7 - *S1/S1; 0,2 - *S1/S2; 0,1 - *S2/S2) and has been widely used for experimental infections in Cameroon27." (PMID 26861587, 2016). "Allelic variations in TEP1 could render mosquito either susceptible or resistant to parasite infection." (PMID 36899431, 2023). "Furthermore, silencing TEP1 in mosquitoes before infection further increases parasite loads in susceptible mosquitoes and abolishes resistance and parasite melanization in refractory mosquitoes." (PMID 28095489, 2017). "Interestingly, CLIPA14 RNAi phenotypes and its infection-induced cleavage were abolished in a TEP1 loss-of-function background." (PMID 28928218, 2017). "Survival assays revealed a significant increase in susceptibility of CLIPA8 and TEP1 kd mosquitoes to B. bassiana over controls, whether gentle dragging or spraying was used to establish an infection." (PMID 23166497, 2012). "To understand the responses of fat body and tissue-associated cells to infection, we performed ISH using probes for DEF1 and TEP1." (PMID 40766253, 2025). "For example, Tep1 is known to play a role in the melanization of parasitoid eggs, and it was expressed more highly in selected populations after infection." (PMID 38206983, 2024). "The TEP1 gene was reported to target the Plasmodium parasite in the early stages of infection in the mosquito host mostly the ookinetes either by melanization or lysis effectively reducing oocysts and sporozoite numbers in the vector." (PMID 35948910, 2022). "Silencing of TEP1 expression produced the same phenotype of increased mosquito mortality after infection with M. anisopliae (p = 0.003, Cox HR = 1.3, 99% CI 1.03–1.5)." (PMID 35428783, 2022). "Their roles in hemocyte TEP1 regulation during infection with CSPmut parasites were determined by RNA silencing." (PMID 35680915, 2022). "TEP1 mRNA levels were significantly upregulated in mosquitoes infected with the mutant parasites at day 5 PI, as compared to that observed for the CSPwt infection." (PMID 35680915, 2022). "Further studies showed that Bs treatment significantly increased TEP1 expression in the fourth-instar larvae (L4), pupae (Pu), 48 h post-infection (hpi) and 72 hpi (P < 0.001)." (PMID 32891162, 2020). "It has been shown that the silencing of DUOX promotes effective immune responses that include the increment of TEP1, leading to lower infection loads." (PMID 31993053, 2019). "SPCLIP1 is required for the recruitment of TEP1 to the surface of E. coli and P. berghei during infection." (PMID 30958840, 2019).
infection (continued). "Second, many antibacterial effectors that are produced by hemocytes also have anti‐Plasmodium activity, including two of the genes that showed larval infection‐induced regulation as adults: CecA and Tep1." (PMID 31161020, 2019). "Lp and Vg proteins are involved in delivering nutrients to nurture oocyte development, and have also been found to reduce TEP1 (thioester-containing protein) expression, thereby resulting in an increased infection with P. berghei." (PMID 31697788, 2019). "In contrast, following G486 infection Tep1 expression increased considerably (comparison of G486 infection to control, main effect wasp infection: F = 178.00, d.f. = 1,84, p<10−10)." (PMID 31589659, 2019). "The data showed that the increase of Δpbp48/45 infection intensities in TEP1 kd compared to dsLacZ injected control mosquitoes was very small, as the median oocyst number in two independent biological replicates was 2 and 1, respectively." (PMID 28729672, 2017). "Upon infection, the C-terminal part of TEP1 binds to the surface of bacteria or Plasmodium ookinetes and promotes their phagocytosis or lysis, respectively." (PMID 28874153, 2017). "These experiments are consistent with the notion that TEP2 and TEP4 are secreted into the haemolymph and undergo proteolytic cleavage upon infection, similarly to what was reported for A. gambiae TEP1." (PMID 28874153, 2017). "Upon bacterial challenge, Tep1, Tep2, and Tep4 are upregulated in D. melanogaster larvae, whereas only Tep1, Tep2, Tep4, and Tep6 are upregulated in adults in response to certain bacterial, fungal, or parasitoid infection." (PMID 28706521, 2017). "We have previously reported that the SPH CLIPA2 is a negative regulator of the TEP1-mediated response by showing that CLIPA2 knockdown (kd) enhances mosquito resistance to infections with fungi, bacteria, and Plasmodium parasites." (PMID 28928218, 2017). "To this end, we performed immuno-histochemical staining of TEP1ΔT;Vg-TEP1r midguts 24h after infection using TEP1 specific antibodies." (PMID 28095489, 2017). "Increased pre-infection levels of TEP1 have been observed following knockdown of the inhibitor of REL1 nuclear translocation; Cactus." (PMID 28420446, 2017). "In our An. gambiae colony silencing TEP1 results in markedly higher infection rates with several P. falciparum strains." (PMID 29041962, 2017). "Using the X1 parental strain from which the TEP1 mutant line was originally derived as a control, oocyst numbers were examined at day 2 and day 8 following infection with fluorescent mCherry P. berghei parasites." (PMID 28764765, 2017). "In An. gambiae, TEP1 is constitutively expressed prior infection and is upregulated by 1.8–2.5-fold at 24 h post P. berghei infection." (PMID 28761783, 2017). "Evidence to support this model included immuno-histochemical staining of mosquito tissues that showed TEP1 accumulation inside hemocytes, particularly after bacterial challenge and 24-48h after infection with P. berghei." (PMID 28095489, 2017). "We determined the degree of resistance of the L3–5 mosquitoes to infection with P. falciparum isolates and assessed the contribution of the complement-like factor TEP1 to this resistance." (PMID 26861587, 2016). "Two independent infections with P. berghei parasites confirmed the functional efficiency of TEP1 depletion." (PMID 26861587, 2016). "The LRIM1/APL1C heterodimer protects A. gambiae from infection by binding the complement-like protein TEP1 to form a stable and active immune complex." (PMID 25775123, 2015). "To examine the effect of TEP1 dosage in the process of parasite killing, we compared oocyst infection levels between TEP1 heterozygous mutant, homozygous mutant and control mosquitoes." (PMID 23977401, 2013). "Fourth, we found that no matter how concentrated or dilute a P. falciparum-laden blood meal, silencing caspar still greatly reduced the resulting oocyst infection and, conversely, silencing tep1 significantly increased the infection." (PMID 22685401, 2012).
infection (continued). "Depletion of TEP1 by RNA interference (RNAi) renders mosquitoes hypersusceptible to Plasmodium infections, resulting in abnormally high infection levels." (PMID 20652016, 2010). "TEP1 silencing in An. gambiae (Keele strain) mosquitoes enhances infection with P. falciparum (NK54 strain), doubling the median number of oocysts." (PMID 19643026, 2009). "We also observe that co-silencing two factors, FBN9 and TEP1, together with caspar did slightly increase infection intensity compared to either the TEP1+caspar or FBN9+caspar group (median = 39 oocysts)." (PMID 19282971, 2009). "There is a broad spectrum of compatibility, the extent to which the mosquito immune system limits infection, between different Plasmodium strains and particular mosquito strains that is mediated by TEP1/LRIM1 activation." (PMID 19643026, 2009). "Thus, we demonstrated that infection with CSPmut parasites significantly induced TEP1 expression in a Toll pathway-dependent manner, which is closely associated with the melanization of mature mutant oocysts." (PMID 35680915, 2022). "Interestingly, our results showed that transcription of TEP1 was significantly up-regulated three days post DENV2 infection." (PMID 34054842, 2021). "When comparing between the normal mosquitoes and the GFP-dsRNA injected mosquitoes, the infection intensities were significantly increased by TEP1-dsRNA injection both in the control and Bs groups, which indicated that TEP1 plays a key role in the innate immunity of An. dirus against P. yoelii." (PMID 32891162, 2020). "Microarray analysis of the differentially regulated genes in D. melanogaster larvae responding to symbiotic Heterorhabditis bacteriophora identified Tep2 among the 100 most enriched genes as well as Tep1, and the C3 homolog Tep3 and Tep4 were also induced by infection with these nematode parasites." (PMID 32013030, 2020). "Similar to the work with H. bacteriophora, infection of D. melanogaster larvae with the entomopathogenic nematodes Steinernema carpocapsae containing their symbiotic Xenorhabdus nematophila bacteria leads to high levels of induction for Tep1 and Tep2, which remains steady during the infection." (PMID 32013030, 2020). "Among these gene products, APL1, LRIM1 and TEP1 are associated with TEP1-mediated parasite killing, a process that does not appear to be functional during infection of A. stephensi with P. y." (PMID 33255333, 2020). "This suggests that although TEP1 is universally required for defense against diverse infections, other components may be pathogen-specific." (PMID 30958840, 2019). "CLIPA14 infection-induced cleavage is clearly dependent on TEP1 and its positive regulator SPCLIP1, which further supports our previous observation that SPCLIP1 acts upstream in the TEP1 pathway whereby it seems to regulate the amount of active TEP1 that is deposited on microbial surfaces." (PMID 28928218, 2017). "In comparisons of oocyst numbers in control and mutant lines, oocyst survival was significantly reduced in the period between day 2 and day 8 post-infection, suggesting that the loss of TEP1 does not interfere with the mechanisms of oocyst killing." (PMID 28764765, 2017). "Then at 48 h PI, the TEP1 transcript level falls back to as it was before infection." (PMID 28761783, 2017). "Since TEP1 binds to and kills P. berghei and P. falciparum midgut stages, it is postulated that TEP1 expression is induced in the fat body to replenish the protein in the hemolymph after infection." (PMID 28761783, 2017). "Interestingly, silencing of the members of the complement-like system, including TEP1, LRRs and NOX5/HPX2, renders these resistant mosquitoes fully susceptible to infections with P. berghei, demonstrating the key role in this defense mechanism." (PMID 26861587, 2016). "This may be relevant to immune responses based upon basal immunity, as is indicated in the case of Plasmodium, compared to responses based upon infection-induced upregulation of TEP1 expression." (PMID 23055931, 2012).
infection (continued). "Binding of mature TEP1 to the parasite surface is one of the first steps leading to parasite killing; either increasing or reducing this event greatly influences the outcome of infection." (PMID 20652016, 2010). "Interestingly, the TEP1 kd group succumbed more quickly to infection than the CLIPA8 kd, suggesting that TEP1 might be controlling more than one anti-fungal effector mechanism." (PMID 23166497, 2012). "The results showed that TEP1, LRIM1, and APL1C were significantly increased by DHA treatment at 24 and 72 h post infection (hpi) compared with those in the control group." (PMID 39363238, 2024). "The results showed mean/median infection intensities of 238.1/200 (92% infection prevalence) in LRIM1 and 397.5/397 (100% infection prevalence) in TEP1 silencing." (PMID 28729672, 2017). "The infection prevalence also increased from 16% and 8% in dsLacZ-injected controls to 96% in LRIM1 and 89% in TEP1 knockdown mosquitoes, respectively." (PMID 28729672, 2017). "Over-activation of the JNK pathway, by silencing its suppressor Puckered, enhances midgut nitration and greatly reduces the intensity and prevalence of infection, an effect that is reverted by co-silencing HPX2, NOX5 or TEP1." (PMID 28729672, 2017). "Two anti-Plasmodium factors of Anopheles, thioester-containing protein 1 (TEP1) and nitric oxide synthase (NOS), play a role in the refractoriness of Anopheles towards Plasmodium infection and are generally expressed during infection." (PMID 28761783, 2017). "In the course of similar gene-silencing experiments for LL3, we uncovered that LL3 did not influence infection intensity or oocyst survival in the TEP1 mutant background." (PMID 28764765, 2017). "This, together with the TEP1-dependent reduction of SPCLIP1 from the hemolymph following LRIM1 kd, led us to hypothesize that SPCLIP1 is recruited to the parasite surface during infection." (PMID 24039584, 2013). "The kinetics of TEP1-F reduction demonstrate that this form of TEP1 is consumed quickly in the immune response to infection, in contrast to TEP1cut, which does not seem to vary significantly during that process, at least within the examined timeframe." (PMID 24039584, 2013). "These experiments showed that the requirement of a given pathway component or effector, assessed by RNAi, is often dependent on that average infection intensity (but not always, as evidenced by Caspar and Tep1)." (PMID 22685401, 2012). "Such a finding would suggest the possibility of strain-specific or infection stage-specific mechanisms governing CLIPC9 activation given that the late-phase response does not require TEP1 and our observation that CLIPC9 is cleaved downstream of the TEP1-dependent CLIP-SPH pathway." (PMID 33045027, 2020). "In addition, analysis of RNA expressed by hemocytes using microarrays has shown that TEP1 transcript is present in these cells, but not enriched compared to whole female tissues, and is not further induced by infection." (PMID 28095489, 2017). "In addition, infection intensities and different mosquito/Plasmodium model influence gene expression and anti-Plasmodium responses, except for TEP1 activity that is not affected by infection intensity." (PMID 28761783, 2017). "Furthermore, silencing TEP1 in An. gambiae (G3 strain) does not enhance infection with P. falciparum (NF54 strain), indicating that there are differences in compatibility between particular strains of An. gambiae and P. falciparum (M. Povelones and A. Molina-Cruz, unpublished)." (PMID 19643026, 2009). "Levels of Tep1, PPO6, and RpS7 were not significantly affected by a larval infection." (PMID 31161020, 2019).
cancer (19 papers, 2013 to 2025). A tumor composed of atypical neoplastic, often pleomorphic cells that invade other tissues. "Genetic variants of TEP1 have already been studied concerning cancer risk, including the risk and prognosis of bladder and breast cancer." (PMID 35892421, 2022). "We found that with respect to the other cell lines, Tu42 cells downregulated the tumor suppressor PTEN/MMAC1/TEP1 (PTEN, phosphatase deleted on chromosome ten; MMAC1, mutated in multiple advanced cancers; TEP1, tensin-like phosphatase)." (PMID 31013771, 2019). "PTEN (also known as MMAC-1 or TEP-1) is one of the most frequently mutated tumor suppressors in human cancer and is an important regulator of proliferation, differentiation, and apoptosis." (PMID 28559385, 2017). "In the cancer risk analysis, because TEP1: rs2228042 and rs2229101 exhibited high linkage, the former was included in the analysis." (PMID 28233473, 2017). "TEP1 is one of the telomeres length genes that is linked with cancer." (PMID 33324444, 2020). "As an important component of the telomerase complex, TEP1 has emerged as a potential target for cancer therapy." (PMID 40583858, 2025). "According to the researchers, higher TEP1 expression correlates with telomerase activity in cancer cells." (PMID 35892421, 2022). "The human tumor suppressor, PTEN/MMAC1/TEP1 (PTEN, phosphatase deleted on chromosome ten; MMAC1, mutated in multiple advanced cancers; TEP1, tensin-like phosphatase) is a dual-specificity phosphatase based on the conserved catalytic domain." (PMID 34335554, 2021). "Previous studies indicated the role of cellular vault proteins (MVP, TEP1, vPARP) in the resistance of cancer cells to various anticancer drugs." (PMID 34829999, 2021). "Both ADAM11 and TEP1 had relatively higher evolutionary rates in extremely large carnivores than small ones and suggested an enhanced ability to suppress cancer." (PMID 34107880, 2021). "PTEN/MMAC1/TEP1 is the most frequently inactivated tumor suppressor gene in sporadic cancer and acts by inhibiting cancer cell proliferation and invasiveness and promoting apoptosis through its antagonism of PI3K." (PMID 31013771, 2019). "In BTBD2-TEP1, TEP1 is a well-known GBM suppressor gene, and the deletion/mutation of this gene has been observed in many cancers, including GBM; polymorphism of BTBD2 is involved in the double-strand break repair pathway that can be useful for GBM survival." (PMID 23940583, 2013). "Various studies have demonstrated the involvement of TEP1 in malignant tumor progression." (PMID 40583858, 2025). "Additionally, fifteen genes were associated with cancer control; among these, three were related to immunity (MAGT1, RFXANK and SKAP2), two (ADGRL3 and TENM3) were related to cell adhesion, and two (ADAM11 and TEP1) were found to be tumor suppressor genes." (PMID 34107880, 2021). "This confirmed that REEP3, REEP4, TEP1, and EEPD1 and their network proteins were involved in immunoregulatory functions and cancer development." (PMID 37818043, 2023). "Taken together, REEP3, REEP4, TEP1, and EEPD1 were related to many cellular functions including cell proliferation, differentiation, the pathogenesis of neurological disorders and cancer biology." (PMID 37818043, 2023). "Taking advantage of Gene Expression Profiling Interactive Analysis (GEPIA) and The Cancer Genome Atlas Program (TCGA), we compared mRNA expression of REEP3, REEP4, TEP1, and EEPD1 between GBM tumor and normal brain tissue." (PMID 37818043, 2023). "In addition, we identified 15 cancer-related REGs in extremely large carnivores, including two tumor suppressor genes—ADAM11 and TEP1, of which ADAM11 was still significant after FDR correction." (PMID 34107880, 2021). "In patient P4, two of four malignant ascites-emerging clones may be targetable by inhibitors against BRAF (e.g. Vemurafenib), TEP1, ERBB4, PIK3CA, HDAC9, or FYN." (PMID 26811494, 2016).